WNK1 (WNK lysine deficient protein kinase 1)
Diseases named in the same sentence as WNK1 in open-access papers (continued):
Sharing a sentence is not in itself a finding about the gene and the disease.
cancer (49 papers, 2012 to 2026). A tumor composed of atypical neoplastic, often pleomorphic cells that invade other tissues. "Treatment with PV-10 also consistently reduced phosphorylation of WNK1, which has been implicated in cancer cell migration and autophagy inhibition." (PMID 38672602, 2024). "WNK1 has been implicated in tumor cell migration and invasive characteristics in breast, lung, and prostate cancers." (PMID 38672602, 2024). "The lysine-deficient protein kinase-1 (WNK1) is a critical protein in both embryonic- and cancer-induced angiogenesis and is considered a potential therapeutic target to contrast cancer progression." (PMID 37233501, 2023). "Instead, STMN1 and the microtubule-associated kinase WNK1 are also involved in cell cycle control, cell survival and apoptosis, as components of diverse cancer signaling networks including PI3K/AKT, TNF and NF-κB signaling." (PMID 37305581, 2023). "Analyses of mouse models and patient data have implicated the protein kinase WNK1 as one of a handful of genes uniquely linked to a subset of invasive cancers." (PMID 35813203, 2022). "The impaired invasive phenotype of WNK1-depleted cancer cells was linked to downregulation of the EMT-associated transcription factor Slug which was partially rescued by overexpressing the WNK1-regulated kinases OSR1 or SPAK." (PMID 35813203, 2022). "The WNK1 (WNK lysine deficient protein kinase 1) protein is a serine/threonine protein kinase with emerging roles in cancer." (PMID 25171174, 2014). "Previous studies have illustrated that WNK1 may also be a key kinase implicated in various types of cancer." (PMID 36618969, 2022). "To date, several WNK1 mutations have been associated with cancer although their contribution to tumor initiation is unknown." (PMID 29930759, 2018). "The electroneutral Na+/HCO3− cotransporter NBCn1, that has been associated with cancer, could also be a downstream target of the WNK1/SPAK pathway." (PMID 29930759, 2018). "In addition, in vitro studies clearly implicate WNK1 in cell migration, division and differentiation, possibly through the MAP kinase pathway, and large scale sequencing studies have shown a link between somatic mutations of WNK1 and several types of cancer." (PMID 22701532, 2012). "Deregulation of these processes may underlie the effects of WNK1 mutations in cancer." (PMID 29930759, 2018). "At the protein level, SIAH2 regulated glycolytic enzymes and WNK1/hypoxia-inducible factor-1α (HIF-1α) signaling, effects that were amplified by cancer-associated fibroblast (CAF)-derived conditioned medium." (PMID 41596707, 2026). "Our findings indicate that the majority of hub genes were overexpressed in malignant tumor samples in which WNK1 was overexpressed most significantly detected by qRT-PCR." (PMID 40510161, 2025). "TDO2 serves as the main enzyme metabolizing tryptophan in cancer‐associated fibroblasts (CAFs), with the produced kynurenine inducing EMT and cancer cell migration via the AKT/WNK1 axis." (PMID 40103267, 2025). "In recent years, more and more evidence shows that WNK1 is a key kinase involved in many types of cancer, promoting cell proliferation and inducing cancer through anti-apoptosis and promoting survival function." (PMID 37652923, 2023). "WNK1 has been involved in certain types of cancer and has been reported to act upstream of the MEK5–ERK5 module, which has also been implicated in the pathophysiology of various neoplasias." (PMID 37029785, 2023). "The upregulation of WNK1 protein can lead to the activation of its downstream pathway and the increase of potential cancer promotion." (PMID 37652923, 2023).
cancer (continued). "From these results, we proposed a schematic representation of the signaling pathway involved in the inhibition of cancer growth by UA-modulation of the AKT/WNK1 axis." (PMID 36212467, 2022). "WNK1 has been shown to promote tumorigenesis in cancers through its ability to promote cell proliferation via anti-apoptotic and pro-survival functions." (PMID 35813203, 2022). "Here we summarize the structure and turnover of WNK1 protein and evidence for its actions in tumor malignancy in human cancers." (PMID 35813203, 2022). "Recent data have shown that WNK1 signaling pathways are additionally involved in angiogenesis, cancer proliferation, and metastasis." (PMID 36232920, 2022). "In both endothelial cells and cancer cells, WNK1 has the capacity to induce migration and enable transition towards a mesenchymal phenotype." (PMID 35813203, 2022). "In vivo analysis using mouse and zebrafish models indicated that WNK1 accelerated cancer metastasis in HCC and prostate cancer and performed great values in angiogenesis." (PMID 36618969, 2022). "In recent years, there is growing evidence that WNK1 is a critical kinase involved in various types of cancer, but the exact mechanisms by which WNK1 modulates tumor progression are not well understood." (PMID 35813203, 2022). "Evidence generated from several studies suggests that WNK1 is a key in cancer cell migration via regulation of EMT." (PMID 35813203, 2022). "Upregulation of WNK1 protein can result in increased activation of its downstream pathways and potential cancer-promoting actions." (PMID 35813203, 2022). "In LC-associated fibroblasts (LCAF), the activity of TDO1 and IDO1 is increased by a carbohydrate-binding protein Galectin-1, promoting LCAF-derived Kyn in the TME and further activating Akt-WNK1 signaling in cancer cells." (PMID 36123332, 2022). "Our results support the working model that the WNK1–SPAK/OSR1 axis is indeed involved in tumor-induced angiogenesis in both cancer cells and endothelial cells." (PMID 36292952, 2022). "This kynurenine/TDO2 signaling was found to promote cancer growth and invasion, while suppressing the differentiation of dendritic cells through the AKT/cAMP response element-binding protein (CREB)/ WNK Lysine Deficient Protein Kinase 1 (WNK1) axis." (PMID 33540679, 2021). "Inhibition of the AKT/CREB pathway prevents cancer proliferation, while inhibition of the AKT/ WNK1 reverted epithelial-to-mesenchymal transition and cancer migration induced by kynurenine." (PMID 27050278, 2016). "WNK1 is a serine/threonine kinase which plays an initial role in cancer development, including tumorigenesis, cell proliferation, migration, invasion and metastasis." (PMID 27050278, 2016). "In the past, all research on WNK1 has focused on its function in cancer cell proliferation, differentiation, migration and apoptosis." (PMID 25171174, 2014). "The zebrafish model was used in a very recent study to demonstrate how the co-administration of oligo-fucoidan could improve the anti-cancer efficacy of WNK463 (a WNK1 inhibitor) and rafoxanide (an OSR1 inhibitor) in advanced hepatocellular carcinoma." (PMID 37233501, 2023). "A recent study has hinted that actions of WNK1 on calcium homeostasis may participate in cancer progression." (PMID 35813203, 2022). "The control WNK1 exerts over ion transport is a significant factor in its actions in cancers but may be overshadowed by its potential impact on cell phenotype." (PMID 35813203, 2022). "Recently, there has been growing interest in involvement of WNK1 in cancers." (PMID 35813203, 2022). "Our results reveal the WNK1–OSR1–PPP2R1A axis plays a critical role in both endothelial and hepatoma cells during tumor-induced angiogenesis promoting cancer cell migration, and uncover the molecular mechanisms with WNK1 and its downstream effectors during tumor-induced angiogenesis." (PMID 36292952, 2022). "WNK1 was also reported to be involved in PI3K-AKT pathway activation in several cancers." (PMID 36212467, 2022).
cancer (continued). "In addition to its great value in vascular biology, WNK1 has been presented to promote migration of cells involved in multiple cancer types." (PMID 36618969, 2022). "Thus, diverse studies place WNK1 as a regulator of EMT during the invasion of different types of cancer cells." (PMID 35813203, 2022). "Since the initial finding through in vitro scratch wound healing assays that knockdown of WNK1 reduced migration of mouse neural progenitor cell line C17.2 accompanied by morphological changes, numerous studies have identified WNK1 regulation of the migratory phenotype in cancer cells." (PMID 35813203, 2022). "It should be clear that WNK1 has related actions in angiogenesis and cancer." (PMID 35813203, 2022). "Further supporting the possibility of targeting MYC-dependent cancer cells through WNK1 inhibition, we find evidence in an orthogonal drug repurposing screen that cells with high expression of MYC or dependence on MYC have increased sensitivity to PP121 treatment." (PMID 33328249, 2021). "WNK1 is a positive regulator of canonical Wnt/β-catenin signaling in cancer cell line." (PMID 32131390, 2020). "By regulating water, electrolyte and pH homeostasis, as well as receptor trafficking (including glucose transporters) at the cell surface, WNK1 may also play a role in the metabolic adaptation of cancer cells to their microenvironment." (PMID 29930759, 2018). "Moreover, knockdown of WNK1 by siRNA transfection prevented cancer migration mediated by LCAF-CM and Kyn." (PMID 27050278, 2016). "The 12 p13.33 amplicon encodes the intriguing candidate WNK1, a member of the WNK family of serine/threonine kinases which affect MAPK signaling and a variety of cancer hallmarks including cell cycle progression, evasion of apoptosis, invasion and metastasis, and metabolic adaptation." (PMID 22860045, 2012). "The WNK1-selective inhibitor WNK-IN-11, had only modest effects on the disassembly–reassembly process (it inhibits only one of the four WNK kinases) but caused a dramatic and rapid (within 1 h) spheroid to fibril transition of GFP-MxA condensates in three different cancer cell lines." (PMID 40643468, 2025). "Nonetheless, whether PPP2R1A is downstream of WNK1 in angiogenesis and cancer remains obscure." (PMID 36292952, 2022). "In addition to activating signaling pathways in cancer cells, WNK1 might participate in cancer formation through angiogenesis." (PMID 36292952, 2022). "However, the role of WNK1/4-ERK1/2 signaling in cancer is unclear." (PMID 36123332, 2022). "WNK1 is also involved in many pathways, including MAPK, WNT/β-catenin, TGF-β-SMAD2, 5′AMP-activated protein kinase, and PP2A subunit alpha isoform, which contribute to cell proliferation, migration, and angiogenesis, and thus is associated with cancer progression." (PMID 36292952, 2022). "This indicates that novel mechanisms, such as WNK1 activation, may contribute to prosurvival activity of HGF in MET-amplified NSCLC cells and maintain the tumor-promoting crosstalk between tumor cells and cancer- associated fibroblasts." (PMID 28968967, 2017). "Moreover, WNK1 has been identified as an important kinase involved in development and cancer." (PMID 24555568, 2014). "Taken together, these data show that WNK1 is essential for the growth of AML cells, but importantly also for the proliferation of most cancer cell lines tested." (PMID 40425534, 2025). "However, the specific contribution of WNK1 to sustain cancer cells remains unclear." (PMID 40425534, 2025). "In this respect, WNK1 has been reported to interact with PI3K‐AKT, TGF‐β and NF‐κB signalling in cancer." (PMID 37029785, 2023). "Knockdown of AK6 can decrease the expression of WNK1 and CLC3, resulting in increased intracellular Cl− concentration in cancer cells upon hypotonic conditions." (PMID 36123332, 2022). "MiR-93, miR-130a, miR-210a, miR-524a, and miR-620 are found to directly target oncogenic WNK1/3 or antitumor WNK2, thus affecting cancer progression." (PMID 36123332, 2022).
cancer (continued). "In kidney cancer, WNK1 is found to activate TRPC6-induced Ca2+-NFAT signaling, which promotes the proliferation and migration of cancer cells." (PMID 36123332, 2022). "Thus, interfering with WNK1 expression may have therapeutic value in human cancers." (PMID 35813203, 2022). "On the contrary, WNK1-activated OSR1 can phosphorylate Smad2/3 at residues Thr-220/179 and enhance their activity in cancer cells, which activates pro-EMT transcription factors and further promotes the expression of TGF-β1 in an autocrine manner." (PMID 36123332, 2022). "The activation of the Akt-WNK1-SPAK/OSR1 axis upregulates mesenchymal markers Snail and N-cadherin and downregulates epithelial markers E-cadherin, thus promoting cancer EMT." (PMID 36123332, 2022). "We found eight MAPK pathway genes (including MYC, WNK1 and PXN) that are classifiable as “common essential” (see the “Methods” section) among all cancer cell lines." (PMID 33398072, 2021). "Thus, WNK1 signaling cascade may be a multi-purpose target for combination cancer therapy." (PMID 32131390, 2020). "HGF reactivates MET, EGFR and RON phosphorylation and restores AKT, ERK and WNK1 signaling upon MET inhibition, promoting the survival of MET-inhibited cancer cells." (PMID 28968967, 2017). "Targeting KCa3.1 and LRRC8A, along with pathways such as WNK1–AMPK–p38 MAPK and HDAC3, may provide new therapeutic avenues to reeducate and reprogram TAMs within the TME, thereby enhancing the efficacy of cancer immunotherapy." (PMID 40806751, 2025). "Two additional factors that may lead either to apoptosis or survival of cancer cells have been found to increase, and are STAT1 and WNK1." (PMID 41515132, 2025). "Indeed, we found that WNK1 and YES1 is the common shared kinase by these two cancer cell lines that mediates drug resistance in them amongst other." (PMID 37359373, 2023). "In summary, we briefly highlight four points that may be considered in future analyses of the actions of WNK1 and other WNK family members in cancers." (PMID 35813203, 2022). "Although multiple studies revealed that WNK1 is involved in major cancer-related signaling pathways such as PI3K-AKT, TGF-β and NF-κB, little is known regarding how WNK1 contributes to cancer progression." (PMID 35813203, 2022). "WNK1 is found to repress autophagy in Hela and A549 cancer cell lines through complex mechanisms: Through inhibiting AMPK signaling, WNK1 inhibits the phosphorylation and activity of the autophagy kinase ULK1, a key protein complex for the initiation step of autophagy." (PMID 36123332, 2022). "Events related to a single gene, such as WNK1,FBLN5 and RACGAP1, exhibited opposite patterns between tumor and normal samples, indicating that an uneven distribution in the splicing patterns plays different roles in cancer development." (PMID 34130646, 2021). "WNK kinase family fusions (WNK1 and WNK2) were also detected in multiple cancer types." (PMID 29617662, 2018). "It was shown that phosphorylated WNK1 is involved in the regulation of GLUT1 in noninsulin target cells suggesting its role in controlling Warburg metabolism in cancer cells." (PMID 26337468, 2015). "Furthermore, the DepMap database suggests that there is a notable codependence in cell viability between WNK1, NRBP1, and TSC22D2 in certain cancer cell lines, consistent with these components operating within a common pathway, and this was also highlighted in another recent study." (PMID 40668933, 2025). "However, WNK1-induced Smad2 phosphorylation at residue Ser-465 interferes with the TGF-β-induced phosphorylation, nuclear translocation and transcriptional activity of Smad2, thereby inhibiting TGF-β signal transduction in cancer cells." (PMID 36123332, 2022). "With no lysine 1 (WNK1), which may be activated by Akt, is important in cell proliferation and invasion, contributing to carcinogenesis and cancer progression." (PMID 28672809, 2017).
cancer (continued). "In addition, we discovered that erbB4 regulates the phosphorylation of two molecules—with-no-lysine kinase 1 (WNK1), a kinase that is phosphorylated at Thr60 by Akt, and heat shock protein 60 (HSP60)—that promote tumorigenesis in other cancer types." (PMID 31291965, 2019).